LRP1B (LDL receptor related protein 1B)
Diseases named in the same sentence as LRP1B in open-access papers (continued):
Sharing a sentence is not in itself a finding about the gene and the disease.
lung cancer (continued). "Low expression of LRP1B was observed in 26 lung cancer tissues and in 14 benign disease tissues." (PMID 33200540, 2021). "Previously, LRP1B has been studied in lung cancer as well as colon cancer." (PMID 34386813, 2021). "Therefore, further investigation in a large cohort is warranted to validate the distinct prevalence of mutations in EGFR and LRP1B among LUAD patients with COPD and clarify the impact of COPD on the survival of the patients with lung cancer." (PMID 28522810, 2017). "We also identified higher prevalence of LRP1B among the LUAD patients with COPD, which might help understand the underlying mechanisms which link COPD and lung cancer." (PMID 28522810, 2017). "LRP1B was originally discovered during the study of lung cancer cell lines." (PMID 27626682, 2016). "To examine whether MARVELD1 affected NMD, we generated a NMD reporter plasmid carrying a PTC derived from deletion mutation of endogenous LRP1B gene exons 1–9 in lung cancer cell QG56; GFP-coding region was inserted at C-terminal of LRP1B gene." (PMID 25520033, 2014). "Moreover, we constructed the NMD reporter plasmid expressing PTC-containing truncated LRP1B-GFP mRNA (LRP1B exons 1–9 from lung cancer cell line QG56), and demonstrated that MARVELD1 bound PTC-mRNA as efficient as NMD core factor UPF1 and SMG1 by RNA-ChIP based reporter system." (PMID 25520033, 2014). "In the training set, the RNF213, LRP1B, KMT2D and CSMD3 genes had statistically significant differences in the sequenced data in lung cancer compared to benign disease." (PMID 33200540, 2021). "Low-density lipoprotein (LDL) receptor-related protein 1B (LRP1B), a member of the LDL receptor family, is frequently inactivated in multiple malignancies including lung cancer." (PMID 27626682, 2016). "Interestingly, TMB and LRP1B mutation frequencies showed similar trend fluctuations in Lu-NECs, suggesting that LPR1B mutations correlate with high TMB status and may serve as potential predictive indicators for favorable outcomes of immunotherapies in lung cancer." (PMID 40230612, 2025). "In the old lung cancer group, there were genes significantly concurrent with actionable driver genes (CDKN2A, NF1): FAT1, LRP1B, ARID2 with CDKN2A; EPHB1 with NF1, and genes significantly exclusive with actionable driver genes (EGFR, KRAS): MLL2, STK11, KRAS with EGFR." (PMID 35096611, 2021). "The RNF213 gene was mutated in 25% of lung cancer patients and was not mutated in benign diseases, but KMT2D, CSMD3 and LRP1B were mutated less in both groups." (PMID 33200540, 2021).
lung cancer (continued). "As for the genetic landscape in detail, several incidences of mutated genes that were adverse to prognosis were observed to be lower in the young lung cancer group (LRP1B, SMARCA4, STK11, FAT2, RBM10, FANCM), which may explain the better prognosis of the young lung cancer group to some extent." (PMID 35096611, 2021). "The number of missense mutations in the LRP1B, KMT2D, RNF213 and CSMD3 genes was eight (8/27, 29.6%), seven (7/27, 25.9%), seven (7/27, 25.9%) and six (6/27, 22.2%) in the lung cancer group, respectively, and none of the genes were mutated in the benign disease control group." (PMID 33200540, 2021).
non-small cell lung carcinoma (26 papers, 2006 to 2025). A group of at least three distinct histological types of lung cancer, including non-small cell squamous cell carcinoma, adenocarcinoma, and large cell carcinoma. "The immunocyte association analysis of single-sample GSEA in non-small cell lung cancer showed that the LRP1B mutation led to a high level of immune cell infiltration." (PMID 36204371, 2022). "Gene mutations in LRP1B are frequently detected in many cancers, with 12% in non-small cell lung cancer, 11% in head and neck cancer, 9% in cervical cancer, 8% in bladder cancer, and 8% in prostate cancer." (PMID 33994859, 2021). "Interestingly, LRP1B, a gene specifically deleted in non-small cell lung cancer (NSCLC), was mutated in 5/7 patients with the generalized disease (71%), but in none of the patients with solitary metastases (n = 3)." (PMID 33255265, 2020). "The downregulation of LRP1B was observed in non-small-cell lung cancer cell lines and in renal cell cancer tissues and cell lines." (PMID 38612772, 2024). "LRP1B somatic alterations were found in more than 20% of tumor types identified in the Cancer Genome Atlas data, including non-small-cell lung cancer, melanoma, esophageal, gastric, head and neck cancers, and bladder cancers." (PMID 38612772, 2024). "In fact, LRP1B gene also designated as LRP-DIT (LRP-deleted in tumors) was first identified as frequently inactivated in non-small-cell lung cancer cell lines and as a putative tumor suppressor." (PMID 34577535, 2021). "It has been found that nearly 40% of non-small cell lung cancer cell lines are inactivated by LRP1B alterations at the gene and transcriptional levels." (PMID 33933102, 2021). "To assess the effect of LRP1B on the proliferation of non-small cell lung cancer cells, we constructed and expressed a transfection vector containing the 13.800 bp full-length murine Lrp1b cDNA using a PCR-based cloning strategy." (PMID 27626682, 2016). "The low-density lipoprotein (LDL) receptor-related protein 1b (LRP1B) was reported to be deleted in several types of human malignancies, including non-small cell lung cancer." (PMID 20383322, 2010). "LRP1B was initially named LRP-deleted in tumors (LRP-DIT) because in a study of non-small cell lung cancer cell lines (NSCLC) the LRP1b gene was deleted or inactivated in 40% of the cell lines." (PMID 16930455, 2006). "LRP1B can activate multiple carcinogenic pathways and enhance cellular activity, potentially contributing to the poor prognosis observed in hepatocellular carcinoma, non-small cell lung cancer, ovarian clear cell carcinoma, and other tumors." (PMID 39928247, 2025). "LRP1B was reported as a tumor suppressor gene in non-small-cell lung cancer." (PMID 37427142, 2023). "LRP1B gene was identified as commonly inactivated in non-small-cell lung cancer cell lines and its inactivation by several genetic and epigenetic mechanisms has been frequently reported in multiple tumor types, corroborating its proposed tumor suppressor function." (PMID 35841413, 2022). "LRP1B, also known as LRP-DIT (LRP deletion in tumors), was first determined to be frequently inactivated in non-small cell lung cancer (NCLC) cell lines and was considered a putative tumor suppressor." (PMID 35389768, 2022). "LRP1b, initially named LRP-DIT (Deleted in Tumors), was first described as a gene that was frequently inactivated in non-small cell lung cancer." (PMID 20383322, 2010). "Overexpression of Lrp1b in non-small cell lung cancer cells with low or absent endogenous LRP1B expression significantly reduced cellular proliferation compared to empty vector-transfected control cells." (PMID 27626682, 2016).
gastric cancer (19 papers, 2012 to 2026). A primary or metastatic malignant neoplasm involving the stomach. "Missense mutations, nonsense mutations, silencing mutations, frame-shifting deletions, insertions, and frame-missing mutations in LRP1B have been observed in cancers such as lung, skin, and stomach cancer." (PMID 34093808, 2021). "For example, it has been suggested that LRP1B may be a tumor suppressor gene implicated in gastric cancer, and inactivation of LRP1B may enhance thyroid cancer growth by modulating the extracellular environment." (PMID 25945796, 2015). "Through the re-establishment of LRP1B expression (with mini-receptor) in LRP1B-deficient cancer cells, it was observed the suppression of anchorage-dependent growth (in esophageal and gastric cancer cells) and anchorage-independent growth (brain, gastric, thyroid and colon cancer cells)." (PMID 34577535, 2021). "The four prioritized mutations (PTPRK, PIK3CB, LRP1B, and IGF2R) provide new insights into the genetic landscape of gastric cancer and represent promising candidates for the development of targeted therapeutic strategies." (PMID 41696640, 2026). "One study found that gastric cancer patients with PIK3CA, LRP1B and AHNAK2 mutations had a better prognosis, and that investigating the molecular mechanisms of the three-gene interaction has potential value in improving the prognosis of gastric cancer." (PMID 38033502, 2023). "More recently, evaluation of LRP1B expression in gastric cancer patient samples showed that cytoplasmic LRP1B was significantly associated with a low clinicopathological stage and favorable prognosis of patients with diffuse-type gastric cancer, but not with intestinal-type gastric cancer." (PMID 34577535, 2021). "LRP1B is a functional tumor suppressor gene in gastric cancer, and is regulated by DNA methylation." (PMID 30755693, 2019). "The mutation of LRP1B has been identified in various cancers, including hepatocellular carcinoma (HCC), ovarian cancer (OC), glioblastoma (GB), Merkel cell carcinoma, and gastric cancer (GC), and is speculated to play a negative regulatory role in cancers." (PMID 40170839, 2025). "Besides, recent studies have suggested that epigenetic silencing due to aberrant promoter methylation or histone deacetylation may be necessary for LRP1B inactivation in thyroid carcinoma, gastric carcinoma, and renal cell carcinoma." (PMID 34152098, 2021). "The frequency of LRP1B mutation gene is high in many cancers, but its role in gastric cancer (GC) has not been determined." (PMID 38136305, 2023).
hepatocellular carcinoma (18 papers, 2021 to 2025). A malignant tumor that arises from hepatocytes. "Wang and colleagues have found that LRP1B contributed to 12.3% of hepatocellular carcinoma patients with mutated genes in the Chinese cohort." (PMID 38612772, 2024). "One study has suggested that LRP1B mutation is associated with a higher TMB in hepatocellular carcinoma." (PMID 38136305, 2023). "Nevertheless, other studies have shown that the LRP1B mutations are associated with a worse prognosis in hepatocellular carcinoma (HCC) patients and with a poor response to ICI, being also related to TMB and immune infiltration." (PMID 37511044, 2023). "ARID1A and LRP1B are mutated in 10% and 6.4% of human hepatocellular carcinomas within five studies compiled in cBioPortal." (PMID 35557512, 2022). "Previous studies reported that LRP1B mutations were associated with worse prognosis of hepatocellular carcinoma based on analyses of TCGA and Chinese cohorts, but a higher TMB and better immunotherapy outcome in NSCLC." (PMID 35884443, 2022). "Moreover, LRP1B variants have been associated with progression-free survival in patients receiving lenvatinib combined with immune checkpoint inhibitors following early hepatocellular carcinoma recurrence." (PMID 40170839, 2025). "This indicated that LRP1B alterations showed a significant correlation with worse OS outcomes, which was in accordance with studies conducted on hepatocellular carcinoma (HCC)." (PMID 36282125, 2023). "Notably, recent research also suggests LRP1B regulates the PI3K/AKT pathway in Hepatocellular Carcinoma (HCC)." (PMID 38731914, 2024). "Nevertheless, the role and mechanism of the high LRP1B mutation rate in hepatocellular carcinoma are still not fully understood, and we are collecting further data and conducting experimental verification." (PMID 34093808, 2021). "At the very least, our research results pointed out the important relationship between LRP1B and HCC, and provided further research directions for the prognostic indicators of hepatocellular carcinoma and immunotherapy strategies." (PMID 34093808, 2021).
colon cancer (14 papers, 2019 to 2025). "Down-regulation of LRP1B was reported to promote cell growth and migration in colon cancer cells 35, and in renal cell cancer 36, and is associated with acquired chemotherapy resistance in high-grade serous ovarian cancer." (PMID 33994859, 2021). "At the same time, it was suggested that LRP1B was down-regulated in colon cancer tissues and suppressed the cell proliferation, migration and metastasis of colon cancer cells, which was closely associated with β-catenin/TCF signaling." (PMID 34386813, 2021). "LRP1B downregulation in colon cancer tissues prevents colon cancer cells from proliferating, migrating, and metastasizing." (PMID 38612772, 2024). "Colon cancer cells’ development and metastasis ability are significantly enhanced after LRP1B knockdown through β-catenin/TCF signaling." (PMID 35389768, 2022). "LRP1B activity is commonly downregulated during tumor progression in several tumor types, such as renal and colon cancer." (PMID 35389768, 2022). "LRP1B has been reported to be down-regulated in colon cancer tissues, and impedes the proliferation, migration, and metastasis of colon cancer cells." (PMID 32624706, 2020). "In colon cancer tissues, downregulation of LRP1B inhibits the growth, migration and metastasis of colon cancer cells." (PMID 30755693, 2019). "LRP1B may serve as a potential colon cancer therapeutic target, and its absence leads to changes in immune cell infiltration." (PMID 39532036, 2024). "In addition, we discovered that KRAS was mutually exclusive with LRP1B in the left-sided colon tumors." (PMID 36439454, 2022). "Interestingly, LRP1B is among the recently suggested five genes representing a signature with prognostic potential in patients with stage III colon cancer." (PMID 33255265, 2020). "LRP-1B, a member of LDL-R family highly homologous to LRP-1, is downregulated in the colon cancer tissues and inhibits the growth, migration and metastasis of colon cancer cells." (PMID 32582700, 2020).
thyroid cancer (13 papers, 2012 to 2025). "Variant rs10166768 within LRP1B displayed an MAF in thyroid cancer cells similar to the 1KGP samples and in the control cancer cell lines equivalent to the GnomAD reported genotypes, suggesting substantial population heterogeneity." (PMID 39770638, 2024). "Others found somatic mutations and genomic loss of LRP1B in thyroid cancer cell lines and thyroid carcinomas correlated with vascular invasion." (PMID 34680332, 2021). "Among the genes previously implicated in thyroid cancer, LRP1B (LDL Receptor Related Protein 1B) was found mutated in FTC and FVPTC negative cases (cases 27 and 8) and NCOR1 (Nuclear Receptor Corepressor 1) in 2 HCC negative cases (cases 28 and 30)." (PMID 34680332, 2021). "The 6-SNP PRS-based model is composed of DIRC3_rs6759952, GAP43_rs13059137, NRG1_rs7834206, PROM1_rs72616195, LOC100507065_rs11175834, and LRP1B_rs1369535, that is, SNPs related to cell growth and inflammation were found to be positively associated with the risk of thyroid cancer." (PMID 33805984, 2021). "The present study suggested that DIRC3, GAP43, and LRP1B are involved in tumor suppressor activity to inhibit thyroid tumorigenesis, and their mutation may reduce the suppression of thyroid cancer risk." (PMID 33805984, 2021). "Deleteriousness scores calculated using CADD revealed several variants with very high scores, including those in RGPD3, LRP1B, and RET, emphasizing their critical roles in thyroid cancer progression and therapeutic potential." (PMID 40297138, 2025). "LRP1B is an endocytic receptor that acts as a tumor suppressor by constraining the invasive behaviors of thyroid cancer and other cancer cells." (PMID 33805984, 2021). "miR-548 is implied in regulating pancreatic cancer progression and downregulation of low-density lipoprotein receptor-related protein (LRP1B), in thyroid cancer." (PMID 25174825, 2014). "Finally, and given that LRP1B was identified as a secretome modulator in thyroid cancer cells, we investigated the differences in the secretomes of the three GB clones." (PMID 37511044, 2023). "LRP1B ectopic expression inhibited thyroid cancer cell growth and invasion." (PMID 34680332, 2021).